SHBG (sex hormone binding globulin)
Diseases named in the same sentence as SHBG in open-access papers (continued):
Sharing a sentence is not in itself a finding about the gene and the disease.
Insulin resistance (continued). "Based on the current evidence, LCD, particularly long-term LCD and low-fat/low-CHO LCD, may be recommended for the reduction of BMI, treatment of PCOS with insulin resistance, prevention of high LDL-C, increasing the levels of FSH and SHBG, and decreasing the level of T level." (PMID 31885557, 2019). "Insulin resistance has an important role in the mechanism of PCOS in both obese and nonobese women, and hyperinsulinemia in response to insulin resistance increases ovarian androgen synthesis and decreases hepatic sex-hormone binding globulin (SHBG) synthesis resulting in androgen excess." (PMID 31915452, 2019). "Therefore, to estimate the association between SHBG and the risk of NAFLD without the confounding influences of overweight and insulin resistance, we further performed the subgroup analysis after stratifying the whole population by BMI and HOMA-IR status." (PMID 30455723, 2018). "Although the etiology of PCOS is not fully understood, evidence suggests that insulin resistance (IR), with or without compensatory hyperinsulinemia, contributes to inhibit liver sex hormone-binding globulin (SHBG) production and to stimulate ovarian/adrenal androgen secretion." (PMID 30147722, 2018). "Insulin resistance and low rate of SHBG could worsen hyperandrogenism but is not enough to explain virilization." (PMID 30376853, 2018). "We have demonstrated that PCOS has an intrinsic insulin resistance irrespective of obesity; and age, BMI, testosterone and sex hormone-binding globulin could not explain all of the insulin resistance." (PMID 27916865, 2016). "A possible explanation for this finding is that SHBG levels may be the consequence of fetal programming for obesity and/or insulin resistance in adult women, not genetically determined to develop PCOS." (PMID 25790331, 2015). "In PCOS women SHBG levels are often low, independent of obesity and insulin resistance and may contribute to hyperandrogenic phenotype of the syndrome." (PMID 25790331, 2015). "Despite the lack of any overlap between SNPs used in the SHBG and insulin resistance scores, it remains possible that these traits might lie on the same causal pathway, in which case joint interventions might have synergistic effects." (PMID 26416764, 2015). "Furthermore, low levels of SHBG in women with PCOS have been associated with low levels of HDL-cholesterol, independent of insulin resistance and obesity." (PMID 26015809, 2015). "In addition, other surrogate indicators of insulin resistance were not affected by Pioglitazone treatment on day-14, including fasting serum insulin; C-peptide; SHBG; resistin; and adiponectin." (PMID 22412837, 2012). "Moreover, the dynamic during pregnancy of serum T, DHEAS, SHBG, FAI, fasting insulin, GIR and HOMA differed significantly according to the pregnancy outcomes showing an impairment of androgen and free androgen levels and insulin resistance markers." (PMID 20942923, 2010). "Common factors such as abnormal thyroid function, insulin resistance, body weight, age, and concurrent liver disease can all impact the production of SHBG, meaning a total testosterone level may no longer accurately reflect a patient’s bioavailable or physiologic testosterone." (PMID 41179064, 2025). "However, these latter have demonstrated a lack of specificity: for example, SHBG levels could be increased by exogenous estrogen treatment, liver failure, insulin resistance, obesity, and increased growth hormone." (PMID 40259920, 2025). "The decrease in SHBG might not suppress hepatic lipogenesis, thus exacerbating insulin resistance." (PMID 39683532, 2024). "Therefore we do not recommend using SHBG level to diagnose insulin resistance." (PMID 36968815, 2023). "Moreover, SHBG showed a negative correlation with several parameters such as blood pressure, body mass index, waist circumference, insulin, and the homeostatic model assessment of insulin resistance (HOMA-IR)." (PMID 36421197, 2022).
Insulin resistance (continued). "However, insulin as a major factor downregulating SHBG production does not come along with the fact that obese subjects are characterized by insulin resistance, and, to the best of our knowledge, the molecular mechanism by which insulin reduces SHBG production has not yet been described." (PMID 33689083, 2021). "Furthermore, we reported lower levels of sex hormone-binding globulin (SHBG) in the insulin resistant women with PCOS, which is supported by a recent meta-analysis that suggests SHBG having an inverse relationship with insulin resistance in PCOS compared to women without PCOS." (PMID 30377436, 2018). "SHBG may be a key factor related to insulin resistance independent of estradiol and testosterone." (PMID 23825975, 2013). "However, the mechanism regarding the effect of SHBG on insulin resistance has not been clarified." (PMID 23825975, 2013). "Furthermore, SHBG has been reported to affectchanges in estrogen concentration, and in women, subphysiological and physiologicalestrogen concentrations are related to an increased incidence of T2DM, which mayexplain the difference in insulin resistance between men and women." (PMID 40232167, 2025). "Additionally, beyond metabolic factors related to insulin resistance and dyslipidaemia, PCOS was significantly associated with higher baseline levels of oestradiol (E2), LH, DHEAS, testosterone, AMH, FAI, BAI scores and BDI scores and lower SHBG levels, independent of obesity." (PMID 39958263, 2025). "When the patients diagnosed with PCOS + HT were compared with and without insulin resistance, a significant correlation was found between HOMA index, fasting blood glucose, BMI, SHBG and left ovarian volume (p < 0.05)." (PMID 36829146, 2023). "Clinical observations and reports in the literature have suggested a negative correlation between circulating SHBG levels and markers of non-alcoholic fatty liver disease (NAFLD) and insulin resistance." (PMID 33139661, 2020). "A shorter, 8-week case–control study using a supervised treadmill exercise at 60% VO2max for 1 h three days per week reported improved GDR during a hyperinsulinemic-euglycemic clamp and lipid-induced insulin resistance with no change in TT, FAI, SHBG, or FI." (PMID 33467251, 2020). "Increased cortisol and reduced sex hormone binding globulin (SHBG) are both consistent with development of insulin resistance, although hepatic insulin resistance calculated from fasting HOMA did not change significantly." (PMID 22844441, 2012). "Further, insulin resistance, as a common mechanism linking PCOS and sleep problems, could be a key driver of changes in SHBG levels, but it was not explicitly analysed as a confounder with SHBG in previous studies." (PMID 39996383, 2025). "Adipose tissue insulin resistance increases lipolysis, which in turn releases non-esterified fatty acids (NEFAs) and lipid intermediates which fuel gluconeogenesis and lipogenesis, subsequently inhibiting HNF-4α and reducing SHBG production." (PMID 33139661, 2020). "Although differences in insulin resistance estimated by HOMA-IR were not readily apparent between PCOS and non-PCOS women in this non-obese cohort, the level of SHBG, a potential alternative index of insulin resistance, was significantly decreased in non-obese women with PCOS." (PMID 29587769, 2018). "However, this theory may partly explain the results since one recent study found that only SHBG remained a significant predictor of OSA independent of free testosterone, FAI and multiple markers of insulin resistance in women with PCOS." (PMID 39996383, 2025). "However, this again is a contradictory question, as other groups found that low SHBG was a predictor of preeclampsia in infertile PCOS patients, and in an Iranian case–control study, SHBG was even claimed to be a predictor of preeclampsia independent of insulin resistance." (PMID 39410647, 2024).
Obesity (427 papers, 2005 to 2026). Accumulation of substantial excess body fat. "SHBG and, to a lesser extent, testosterone accounted for a modest proportion of the obesity-cholecystectomy association in women." (PMID 41872976, 2026). "Among the mediators related to SHBG levels, obesity, BMI, and waist circumference were independently causally related to endometrial cancer." (PMID 41427029, 2025). "Obesity is associated with marked reductions in SHBG levels, which directly affect testosterone bioavailability." (PMID 41301438, 2025). "In adulthood, SHBG levels are lower with increasing obesity and rise with weight loss and are lower in men, middle aged, and postmenopausal women who have features of MetS." (PMID 40863113, 2025). "BMI, testosterone, and SHBG are independent risk factors for the occurrence of MAFLD in boys with obesity." (PMID 39980852, 2025). "SHBG is synthesized in the liver, and its production is reduced by factors linked to obesity, including insulin resistance and inflammatory cytokines (TNF-α, IL-1β, IL-6)." (PMID 41301438, 2025). "In the presence of obesity, lower SHBG levels cause hyperandrogenism, with insulin and IGF-1 involved in its decrease." (PMID 40278389, 2025). "Related studies have shown that metabolic disorders, including obesity, blood pressure, dyslipidemia, and glycemic traits, are closely associated with circulating SHBG levels and stroke risk." (PMID 40728963, 2025). "The main goal of this study was to consider the role of obesity/overweight as a potential modifier of associations between gene single nucleotide polymorphisms (SNPs) affecting the sex hormone-binding globulin level (SHBGlevel) and uterine myoma (UM)." (PMID 41010401, 2025). "Several studies found that lower levels of SHBG in PCOS patients specifically were negatively associated with obesity, particularly abdominal obesity." (PMID 39941345, 2025). "MR analyses validated that elevated SHBG and testosterone potentially decreased the risk of obesity in males, while hyperandrogenism increased central obesity risk in females." (PMID 41310874, 2025). "Using tertile groupings of total testosterone, estradiol, and SHBG, we examined relationships with 16 obesity-associated markers in male subjects." (PMID 41310874, 2025). "A recent study of women and men in the Netherlands, most with overweight or obesity, reported that genetic variants associated with higher SHBG levels in other populations were associated with lesser amounts of liver fat." (PMID 40863113, 2025). "A growing body of evidence supports the inverse association between SHBG levels and obesity, IR, MetS, MAFLD, T2DM, and PCOS in youth." (PMID 40863113, 2025). "By reducing hepatic SHBG production, hyperinsulinemia sustains elevated levels of bioavailable estrogens that far exceed what would be expected from obesity-associated aromatase activity alone." (PMID 41301707, 2025). "Synthesis of SHBG is controlled by many factors related to obesity, lipogenesis, inflammatory status, and genetic predisposition." (PMID 40427034, 2025). "In males, higher testosterone, SHBG, and T/E2 ratios were associated with a decreased obesity risk, while estradiol and obesity showed an inverted U-shaped relationship." (PMID 41310874, 2025). "Our results indicated that estradiol was positively associated with obesity, while total testosterone and SHBG levels were negatively associated with obesity." (PMID 38524635, 2024). "Low SHBG levels in women are strongly correlated with metabolic syndrome components (such as obesity, lipid profile, IR, and preDM) and are associated with the long-term prognosis of PCOS." (PMID 38374053, 2024). "We observed higher levels of oestradiol and lower levels of SHBG in sons born of mothers with pre-pregnancy overweight and obesity, and these associations were partly mediated by the sons’ own fat mass and BMI." (PMID 37935951, 2024).
Obesity (continued). "It was shown that teenagers with PCOS complicated by NAFLD accounted for 37.5% of the respondents, and those with coexisting obesity and lower SHBG were more predisposed to the development of NAFLD." (PMID 39415788, 2024). "Using data from the National Health and Nutrition Examination Survey (NHANES), we investigated the associations between obesity (measured by WC), sex hormones (testosterone and estradiol), and sex hormone-binding globulin (SHBG)." (PMID 39224565, 2024). "Hyperandrogenemia, low sex hormone binding globulin levels, and obesity are all known to be associated with PCOS and have been linked to an increased risk of developing diabetes and cardiovascular diseases." (PMID 39634187, 2024). "Excitingly, plasma concentrations of SHBG were shown to be associated with insulin concentrations and obesity." (PMID 38725482, 2024). "The elevated insulin levels associated with obesity correspond with decreased levels of the Sex Hormone Binding Globulin (SHBG) in men." (PMID 38892561, 2024). "Low testosterone levels are associated with both IR and obesity, suggesting the independent impact of IR on testosterone synthesis, even when accounting for SHBG levels." (PMID 38892561, 2024). "Obesity in men is linked to elevated estrogen levels and reduced levels of testosterone and sex hormone-binding globulin." (PMID 39359768, 2024). "The proposed mechanisms included the mediation of childhood adiposity, the following predisposition to adulthood obesity, and the subsequent effect of estrogens and SHBG." (PMID 38498127, 2024). "The authors further demonstrated that individuals with obesity and lower sex-hormone-binding globulin (SHBG) levels were more susceptible to developing hepatic steatosis." (PMID 39407944, 2024). "Numerous clinical and experimental studies have convincingly shown that in postmenopausal women, BMI (obesity) is positively associated with both estrogens and androgens (including free ones) and negatively with SHBG." (PMID 38672173, 2024). "Low SHBG levels seen in obesity are caused by the high lipid content of the liver and by high pro-inflammatory cytokines (TNF-α and IL-1)." (PMID 36767197, 2023). "Chronic inflammatory diseases such as polycystic ovary syndrome (PCOS), diabetes or obesity have been associated with low circulating SHBG levels in female patients." (PMID 38146533, 2023). "Obesity, prolonged menstrual cycle, decreased SHBG, and dyslipidemia are risk factors for EH in patients with PCOS." (PMID 37149578, 2023). "This association is partly explained by obesity's detrimental impact on SHBG concentration, because lower SHBG levels enhance testosterone bioavailability." (PMID 37854752, 2023). "Among these 34 traits, 14 were also associated with CKD, indicating the presence of common risk factors between T2D and CKD, predominantly related to obesity, height, blood lipids and sex hormone binding globulin (SHBG), blood pressure, and walking pace." (PMID 37780623, 2023). "Among these 34 traits, 14 were also significantly associated with CKD, indicating the presence of common risk factors between T2D and CKD, primarily related to obesity, height, blood lipids and sex hormone binding globulin, blood pressure, and walking pace." (PMID 37780623, 2023). "In older, obese men, pseudohypogonadism due to obesity is the most common cause for the biochemical constellation of low serum total testosterone (due to low SHBG), normal serum free testosterone, and normal gonadotropins, reflecting a eugonadal state." (PMID 36995891, 2023). "In an all-female cohort study, obesity was associated with lower concentrations of sex hormone binding protein (SHBG), estradiol (E2), and higher concentrations of testosterone (T)." (PMID 36767197, 2023).
Obesity (continued). "According to previous researches, obesity is associated with low total testosterone it is common that free testosterone is normal due to lower SHBG, the relationship between SHBG and free testosterone and SII should be evaluated in future study." (PMID 36051392, 2022). "In men with low serum testosterone attributable to obesity there is a linearly inverse association between decrease in weight and increase in serum testosterone (and SHBG) concentration." (PMID 35834069, 2022). "Decreased sex hormone binding globulin (SHBG) levels are associated with obesity in women, which increases the availability of estrogens and androgens to target tissues." (PMID 36010645, 2022). "Our data demonstrated that PCOS adolescents complicated with NAFLD accounted for 37.5%, and those with obesity and lower SHBG were more predisposed to developing NAFLD." (PMID 36421197, 2022). "We also assessed the effect of the PRS on SHBG, which is influenced by androgen action (as well as by obesity) and observed that a higher PRS was associated with a lower SHBG (β = -0.38 nmol/L decrease per 1 SD of PRS, P = 1 × 10-18)." (PMID 34969092, 2022). "Obesity and hyperinsulinemia have been associated with low levels of sex hormone-binding globulin (SHBG)." (PMID 35813634, 2022). "It should also be noted that decreased SHBG level is an obesity-related disturbance linked to the development of liver IR, and therefore, nutritional status is one of factors indirectly affecting SHBG synthesis." (PMID 35140785, 2022). "In particular, low SHBG serum levels have been associated with high levels of markers of inflammation, and with the risk of onset and progression of obesity, NAFLD and metabolic syndrome (MetS)." (PMID 36421197, 2022). "This cross-sectional study found that exposure to most phthalate metabolites is associated with low SHBG levels and obesity to a greater extent among premenopausal women than postmenopausal women." (PMID 36149653, 2022). "Low SHBG is associated with obesity, hyperinsulinemia, and hyperandrogenism, which are commonly found in PCOS patients." (PMID 34805198, 2021). "Obesity and metabolic endpoints are more closely associated with SHBG than either estrogen or testosterone and SHBG positively correlate with HDL-C levels." (PMID 33918160, 2021). "Among the indicators related to obesity, BMI, waist circumference, insulin and IR were positively correlated with PV levels, while serum TT levels and SHBG were negatively associated with PV levels (P = 0.004 and P = 0.042, respectively)." (PMID 34239023, 2021). "On the other hand, modifications in lifestyle, such as therapy for obesity and weight reduction, caused an increase in circulating SHBG." (PMID 33807959, 2021). "Girls with obesity are at risk for hyperandrogenemia due to increased total testosterone production and reduced sex hormone-binding globulin (SHBG)." (PMID 34828595, 2021). "For example, there is a significant role of SHBG gene polymorphisms on the levels of SHBG independently of obesity, fatty liver and testosterone." (PMID 34244582, 2021). "Obesity and liver fat are associated with decreased levels of serum sex hormone binding globulin (SHBG)." (PMID 33715205, 2021). "Low levels of sex hormone-binding globulin (SHBG) were reported to be associated with obesity, IR, hyperandrogenism, glucose intolerance, and type-2 diabetes in women with PCOS." (PMID 34458674, 2021). "Regulation of SHBG is associated with various factors including age, puberty, obesity, and dietary factors." (PMID 33291623, 2020). "Hypogonadism is also frequently associated with obesity and other metabolic disturbances that can lower the level of SHBG." (PMID 30670838, 2020). "Obesity is found to be associated with lower levels of sex hormone-binding globulin (SHBG), which leads both, to higher bioavailable levels of estrogen and higher insulin levels." (PMID 32977765, 2020).